MYCN (MYCN proto-oncogene, bHLH transcription factor)
Diseases named in the same sentence as MYCN in open-access papers (continued):
Sharing a sentence is not in itself a finding about the gene and the disease.
neuroblastoma (continued). "Inhibition of STAT3 with antisense oligonucleotide or pharmacological inhibitors reduced MYCN gene expression and decreased neuroblastoma tumorigenicity in preclinical mouse models." (PMID 33937011, 2020). "Another study also showed that aberrant amplification of the 350–2000 kb genomic region containing the MYCN oncogene in neuroblastoma increased MYCN levels." (PMID 32382065, 2020). "We identified 13 MYC target genes which were increased in neuroblastoma patients with MYCN amplification in TARGET, GSE19274 and GSE85047 datasets." (PMID 32593299, 2020). "MYCN protein is expressed in most neuroblastoma tumours and significantly influences cell phenotype and patient outcome." (PMID 32707690, 2020). "MYCN-amplified neuroblastoma cell lines are more sensitive to VRK1 inhibition than cells with no MYCN amplification, reinforcing this possibility." (PMID 33233777, 2020). "EV-miR-186 from NK cells induces cytotoxicity to MYCN-amplified neuroblastoma cells; targeted delivery of miR-186 suppresses tumor growth and improves the survival of a orthotopic mouse model of neuroblastoma by targeting MYCN, AURKA, TGFΒR1 and TGFΒR2." (PMID 32503543, 2020). "HDAC11 depletion in MYCN-driven neuroblastoma cell lines strongly induces cell death, mostly mediated by apoptotic programs." (PMID 32719718, 2020). "It has been demonstrated that MYCN-amplified neuroblastoma cells are highly sensitive to BCL2 inhibitors ABT-263 (navitoclax) and ABT-199 (venetoclax)." (PMID 33628735, 2020). "Remarkably, the capability of MYCN to activate the expression of critical oncomirs, such as miR-221, miR-9, or the miR-17-92 cluster, has also been observed in neuroblastoma cells and other types of solid tumor cells." (PMID 33937011, 2020). "In MYCN-amplified neuroblastoma cell lines, MYCN mRNA levels are exceptionally high and they are sufficient for sponge let-7." (PMID 31979076, 2020). "MYCN amplification is observed in about 20% of neuroblastoma and represents one of the strongest clinical predictors of poor prognosis." (PMID 33937011, 2020). "Taken together, a common set of CRC-driven enhancers is found uniquely in MYCN-expressing neuroblastoma cells, indicating that MYCN expression is regulated by the CRC." (PMID 33199677, 2020). "miR-193b targets several important oncogenes including MYCN and is expressed at low levels in neuroblastoma cell lines." (PMID 33614505, 2020). "Collectively, our data suggest interplay between MYCN and c-MYC expression in MYCN-amplified neuroblastoma cells upon glutamine deprivation." (PMID 32483461, 2020). "Consistent with this, decreased BMP4 mRNA in the transgenic Th-MYCN-driven mouse neuroblastoma model, relative to normal ganglia, was also revealed by analysis of a published dataset." (PMID 32210188, 2020). "We next quantified the number of multimodal druggable genes from the MYCN-NA neuroblastoma dataset that correlated with at least one xCell cell type signature." (PMID 32275708, 2020). "When miRs are overexpressed, argonaute‐2‐mediated interaction of miR with MYCN mRNA increases, followed by degradation of MYCN, leading to neuroblastoma regression." (PMID 31637848, 2020). "Whereas MYCN is amplified and highly expressed in about one-third of high-risk neuroblastomas, MYC is highly expressed in a distinct subset of Stage 4 neuroblastomas that have similarly aggressive clinical behavior." (PMID 33425720, 2020). "We previously reported that MYCN mediates GPC2 expression in neuroblastoma and that GPC2 was overexpressed in neuroblastomas that have 7q gains, where the GPC2 locus is." (PMID 32211329, 2020). "Using neuroblastoma SHEP-21 N cell line with ectopic expression of MYCN or shRNA mediated silencing of MYCN, the functional MYCN signatures were revealed." (PMID 32593299, 2020). "miRNA let-7 is a strong negative regulator of MYCN expression and can inhibit proliferation and clonogenic growth of MYCN-amplified neuroblastoma cells." (PMID 33614505, 2020).
neuroblastoma (continued). "Similar results have been described in neuroblastoma, where MYCN-amplified cells display a distinct metabolic structure defined by high energy consumption and production compared to MYCN non-amplified neuroblastoma cells." (PMID 33585251, 2020). "Poor prognostic factors in children with neuroblastoma include: age > 18 months at time of diagnosis, unfavorable histology, increased vascularization, and MYCN amplification." (PMID 32850011, 2020). "MLN8237 destabilizes N-MYC and synergizes with BCL2/BCLxL inhibitor (venetoclax or navitoclax) to kill MYCN-amplified tumor cells including neuroblastoma and rhabdomyosarcoma." (PMID 33614505, 2020). "Here, we show that CYC065 (fadraciclib), a clinical inhibitor of CDK9 and CDK2, selectively targeted MYCN-amplified neuroblastoma via multiple mechanisms." (PMID 33016930, 2020). "In MYCN amplified neuroblastoma models, ATR has also been proposed to play a role in resolution of transcription/replication conflicts." (PMID 32375866, 2020). "This indicates that, despite the possible relationship between VRK1 and MYCN, VRK1 expression strongly correlates with neuroblastoma unfavorable prognosis and aggressiveness independently of the MYCN amplification status." (PMID 33233777, 2020). "Hydra analysis of the TARGET MYCN-NA neuroblastoma cohort found differential expression of tumor microenvironment markers, including markers of the adaptive immune response." (PMID 32275708, 2020). "Rutin obviously abrogates MYCN expression and suppresses the migration and invasion of human neuroblastoma cells, LAN-5." (PMID 32823876, 2020). "The MYCN, a member of the MYC family, has been associated with high-risk disease and poor prognosis in approximately 25% of cases of neuroblastoma." (PMID 32963529, 2020). "One of the most well‐known prognostic indicators for neuroblastoma is genomic amplification of MYCN (Homo sapiens v‐myc myelocytomatosis viral‐related oncogene, neuroblastoma derived), present in ~20% of patients." (PMID 32945147, 2020). "The bexarotene result was particularly interesting because retinoids are an effective treatment for neuroblastoma (i.e., they reduce MYCN expression and induce differentiation)." (PMID 32060267, 2020). "Given the evidence linking VRK1 to tumor progression and the connection with MYCN, we decided to analyze the contribution of this protein to neuroblastoma cell biology, focusing on its pathological significance and prognostic value." (PMID 33233777, 2020). "Although developed in MYCN-amplified neuroblastoma models, this compound shows promising effects on cell cycle and MYC/MYCN stability." (PMID 33585252, 2020). "Aygun and Altungoz showed that c-MYB is involved in the control of MYCN amplification in MYCN-amplified neuroblastoma cell lines." (PMID 33614505, 2020). "To inactivate ATRX in the MYCN-amplified neuroblastoma cell lines, we designed and validated two guide RNAs (gRNA-2 and gRNA-5) to exon 6 of ATRX." (PMID 32060267, 2020). "In neuroblastoma, the most common solid tumor of childhood, elevated N-Myc levels are often found due to amplification of the coding gene, MYCN, which is correlated with poor overall survival of affected patients." (PMID 32346009, 2020). "MYCN is frequently activated in neuroblastoma, a paediatric solid malignancy that, in its metastatic form, has a very poor prognosis." (PMID 31900399, 2020). "Neuroblastoma patients with MYCN amplification and high EIF4G1 expression demonstrated worse clinical outcomes in TARGET dataset." (PMID 32593299, 2020). "The cytoprotective role of AXL has been recognized in different tumor types, including non-MYCN–amplified neuroblastoma." (PMID 32962733, 2020). "The role of Rac2 in blocking macrophage differentiation in MYCN driven mouse model of neuroblastoma has been reported before." (PMID 32722460, 2020).
neuroblastoma (continued). "miR-506-3p is a potent differentiation inducer and a strong repressor of MYCN expression in neuroblastoma cells by targeting PLAGL2 transcription factor." (PMID 33614505, 2020). "In MYCN-amplified neuroblastoma, MYCN invaded active enhancers, driving a transcriptionally encoded adrenergic gene expression program that was selectively reversed by CYC065." (PMID 33016930, 2020). "DNA FISH with neuroblastoma tissues or patient‐derived bone marrow cells is the standard clinical practice for the detection of MYCN amplification." (PMID 32896084, 2020). "We further confirmed the reciprocal regulation between endogenous PLAGL2 and MYCN in multiple neuroblastoma cell lines." (PMID 32087738, 2020). "In MYCN-amplified neuroblastoma, THZ1 treatment led to preferential downregulation of SE-associated genes, including MYCN, thus inhibiting the autoregulated suppression of MYCN-driven global transcription amplification." (PMID 32382065, 2020). "Targeting RBPs is clearly a strategy one can engage with to target key RNAs that we know are crucial in neuroblastoma oncogenic signalling, and perhaps indirectly drug MYCN signalling." (PMID 32707690, 2020). "In another preclinical model, OTX015 was shown to be effective against both in vitro and in vivo MYCN-driven neuroblastoma model." (PMID 33324552, 2020). "From this analysis, we nominated the unstudied protein CAMKV as a putative immunotherapeutic target for MYCN amplified neuroblastoma." (PMID 32211329, 2020). "In another report, αvβ3 integrin is reported to be expressed on 68% of microvessels in MYCN amplified stage 3 neuroblastoma and 34% in MYCN-non amplified tumors." (PMID 32722460, 2020). "We showed earlier that tumors with ATRX deletions tend to have higher adaptive immune expression, and we found a similar pattern in an independent set of MYCN-NA neuroblastoma samples." (PMID 32275708, 2020). "In a validation test, the mTOR pathway was activated on the protein level in MYCN-driven neuroblastomas in mice and activation of MYCN in SH-EP MYCN-ER cells resulted in high sensitivity to mTOR inhibition was observed." (PMID 32117438, 2020). "We showed that MYC knockdown increased MYCN protein, but the cells did not regain their proliferative properties, suggesting that 13-cisRA-resistant cells are addicted to c-MYC, which functionally replaces MYCN in 13-cisRA-resistant neuroblastoma." (PMID 32409685, 2020). "The high expression levels of E2F1 were observed in neuroblastoma patients with MYCN amplification in TARGET, GSE19274, GSE73517, GSE49710 and GSE85047 datasets." (PMID 32593299, 2020). "BET inhibitors, such as JQ1 and OTX015, can displace the BRD4 oncoprotein from chromatin, which potently represses MYCN transcription in neuroblastoma cell lines and effectively reduces neuroblastoma cell viability in vitro and in vivo." (PMID 33614505, 2020). "Here we further investigated the function of miR-506-3p in regulating MYCN expression in additional neuroblastoma cell lines with distinct genetic backgrounds." (PMID 32087738, 2020). "The results presented in this investigation demonstrate that a newly developed ADC targeting LGALS3BP has the potential to eradicate metastatic and MYCN amplified neuroblastomas in preclinical mouse models." (PMID 33076448, 2020). "Upon the addition of doxycycline (Dox), PRMT1 was efficiently depleted in MYCN-amplified human neuroblastoma cell line Kelly, as demonstrated by western blot in two independent shPRMT1 constructs-transduced cells." (PMID 32415090, 2020). "Amplification of the proto-oncogene MYCN is well established as an adverse prognostic marker in neuroblastoma." (PMID 33117806, 2020).
neuroblastoma (continued). "Here, we show that neuroblastoma-specific CRC-driven enhancers contribute to MYCN amplicon structure in neuroblastoma and retain the classic features of active enhancers after genomic amplification." (PMID 33199677, 2020). "Prior studies showed that MYCN can drive MDM2 expression in neuroblastoma cells, which we corroborated in SH-SY5Y neuroblastoma cells with ectopic MYCN overexpression." (PMID 33425720, 2020). "An increase in MYCN copies in the plasma was consistent with MYCN amplification as assessed by DNA‐FISH to measure MYCN amplification in patients with neuroblastoma." (PMID 32896084, 2020). "NBAS is thought to be involved in golgi-to-ER transport and is typically amplified in MYCN-amplified neuroblastoma tumors." (PMID 33245713, 2020). "Previous studies have reported an increased folate demand in MYCN-amplified neuroblastoma cells mediated by the RFC-1 receptor." (PMID 32850011, 2020). "We discovered that PLAGL2 expression is regulated by MYCN at the transcription level in neuroblastoma cells." (PMID 32087738, 2020). "The oncogene MYCN is critical for tumorigenesis of several types of cancers including neuroblastoma." (PMID 32087738, 2020). "The positive enrichment of MYC transcription factor in MYCN amplified neuroblastoma tissues was also observed in GSE19274 and GSE85047 datasets." (PMID 32593299, 2020). "The present study suggested new prognostic markers of ARMC6, DCTPP1, EIF4G1, ELOVL6 and FBL in neuroblastoma and highlighted the combinational prognostic significance of MYCN amplification and EIF4G1 expression in patients with neuroblastoma." (PMID 32593299, 2020). "A small molecular inhibitor of USP’s deubiquitinase activity, P22077, destabilizes N-MYC, thereby markedly repressing the growth of MYCN-amplified human neuroblastoma cell lines in xenograft mouse models." (PMID 33614505, 2020). "In other developmental contexts, MYCN is known to be a Wnt-induced gene, circumstantially supporting the possible oncogenicity of Wnt signaling in neuroblastoma." (PMID 32210188, 2020). "For example, in MYCN-amplified neuroblastoma, a set of master TFs (HAND2, ISL1, PHOX2B, GATA3 and TBX2) assemble a functional CRC to orchestrate the unique gene expression program in this cancer type." (PMID 33080033, 2020). "Various signaling pathways, including PTEN/PI3K/AKT and RAF/MEK/ERK control stabilization of MYCN and are major mediators of uncontrolled tumor growth, angiogenesis, invasion, apoptosis and cellular metabolism in neuroblastoma." (PMID 32722460, 2020). "Despite the importance of the MDM2-MYCN axis in neuroblastoma and retinoblastoma, it has been unclear if MDM2 promotes MYCN expression in additional cancers and if MDM2 also regulates MYC." (PMID 33425720, 2020). "have previously demonstrated that Mycn has the potential to drive neuroblastoma in a transgenic model mouse model, i.e. Th-MYCN mice, which carry, in their germline, human MYCN cDNA under the control of the rat tyrosine- hydroxylase promoter." (PMID 33585251, 2020). "BRD4 inhibitors are known to inhibit transcription of MYCN, induce apoptosis and impair tumor growth of neuroblastoma." (PMID 32722460, 2020). "The important transcriptional target of MYCN in neuroblastoma is the high mobility group A1 (HMGA1) oncogene." (PMID 33194665, 2020). "The MYCN oncogene is amplified and overexpressed in neuroblastoma, and overexpression of N-myc was observed in one-fourth of patients with neuroblastoma." (PMID 32354028, 2020). "We confirmed that CAMKV is selectively expressed in 7/7 MYCN amplified neuroblastoma cell lines and showed that the transcription of CAMKV is directly controlled by MYCN." (PMID 32211329, 2020). "Gene amplification of MYCN was one of the earliest genetic markers discovered in neuroblastoma and is still one of the strongest predictors of poor prognosis." (PMID 33585251, 2020).
neuroblastoma (continued). "In neuroblastoma, amplification of the MYCN oncogene and inactivation of the ATRX tumor-suppressor gene correlate with high-risk disease and poor prognosis." (PMID 32060267, 2020). "In neuroblastoma, lower SH3TC2 expression level was associated with MYCN amplification and poor survival." (PMID 32637351, 2020). "The ring domain of MDM2 binds to the MYCN mRNA adenylate/uridylate-rich elements (AREs) within the 3’UTR, and thereby increases the MYCN mRNA stability and translation in neuroblastoma cells." (PMID 33291373, 2020). "MYCN belongs to the Myc/Max/Mad/Mnt network of proteins that regulate proliferation, apoptosis, and differentiation, which were amplified in neuroblastoma, small-cell lung cancer and hepatic cancer, respectively." (PMID 33381457, 2020). "ALDH18A1-specific inhibitor, YG1702, inhibits MYCN expression and attenuates the growth of human neuroblastoma." (PMID 33614505, 2020). "Detection of amplification of the MYCN gene is essential for determining optimal treatment and estimating prognosis of patients with neuroblastoma (NB)." (PMID 32896084, 2020). "To determine the subset of genes which were differentially overexpressed in MYCN amplified neuroblastoma, we first used RNA-sequencing data from 150 primary tumors (136 of which were high-risk) and stratified them by MYCN expression." (PMID 32211329, 2020). "MYCN amplification has been found in pediatric cancers including neuroblastoma, rhabdomyosarcoma, medulloblastoma, Wilms tumor and retinoblastoma." (PMID 33628735, 2020). "ALK has also been shown to drive neuroblastoma formation and to potentiate the oncogenic activity of MYCN in neuroblastoma." (PMID 33585251, 2020). "Despite that several molecular prognostic factors with oncogenic potentials have been described in neuroblastoma, only activating ALK mutations and MYCN overexpression were shown to be de novo oncogenic drivers." (PMID 33585251, 2020). "From membrane fractionation and immunohistochemistry, we verified that CAMKV is membranous in MYCN amplified neuroblastoma cell lines and patient-derived xenografts." (PMID 32211329, 2020). "The TME landscape of neuroblastoma differs between MYCN amplified and MYCN-non amplified tumors with the former being “cold” and the latter “hot” and rich in inflammatory cells." (PMID 33050533, 2020). "They studied MYCN-driven transcriptome in 20 cases of primary neuroblastomas and compared the results to those of in vitro inducible MYCN cell model (SH-EP MYCN-ER)." (PMID 32117438, 2020). "Transcriptomic characterisations of neuroblastoma tissues and chromatin immunoprecipitation sequencing in cell lines have identified several key mRNAs, such as MYCN, which work in transcriptional positive feedback loops." (PMID 32707690, 2020). "Consideration of MycN/c-Myc status in selecting neuroblastoma patients for glutamine metabolism treatment will be important to avoid potential radioresistance." (PMID 32483461, 2020). "A total of 3439 immune-related genes were profiled for 247 neuroblastoma patients who differ in demographical and clinical factors, including age, gender, MYCN status, ploidy, stage, and overall (OS) and event-free survival (EFS)." (PMID 32731407, 2020). "We similarly analyzed microarray gene expression data from 250 primary neuroblastomas stratified by MYCN expression." (PMID 32211329, 2020). "Next, we induced the expression of MYCN in ATRX-mutant neuroblastoma cells by using a doxycycline-inducible vector." (PMID 32060267, 2020). "MYCN-amplified tumors exhibited high levels of PRMT1 and PRMT5; knockdown of either PRMT1 or PRMT5 led to downregulation of MYCN and suppression of cell growth, suggesting a dependence of MYCN-amplified neuroblastoma on PRMTs3,4." (PMID 32415090, 2020). "Mice containing MYCN transgene targeted to the neural crest cells develop neuroblastoma with a phenotype very similar to the human neuroblastoma." (PMID 33585251, 2020).